GNPNAT1 (glucosamine-phosphate N-acetyltransferase 1)
Diseases named in the same sentence as GNPNAT1 in open-access papers (continued):
Sharing a sentence is not in itself a finding about the gene and the disease.
tumor (continued). "TCGA-LUAD (n = 513 for LUAD, n = 59 for normal), GSE19188 (n = 45 for LUAD, n = 65 for normal), and GSE32863 (n = 58 for LUAD, n = 58 for normal) were chosen for GNPNAT1 differential expression comparison between tumor and healthy tissues." (PMID 33178836, 2020). "The present study found that GNPNAT1 was highly expressed in LUAD tumor tissue and significantly predicts a poor prognosis." (PMID 33178836, 2020). "Based on these observations, we hypothesize that hsa-miR-1-3p and hsa-miR-26a-5p may act as tumor suppressors in LUAD by inhibiting GNPNAT1 expression." (PMID 39062049, 2024). "Additionally, the correlation between GNPNAT1 expression and immune infiltration within the tumor microenvironment was explored." (PMID 39062049, 2024). "By analyzing GNPNAT1 co-occurrence gene function, we found that GNPNAT1 might participate in multiple tumor cell cycle progression, further influencing tumor cell proliferation and apoptosis." (PMID 33686019, 2021). "GNPNAT1 was upregulated in LUAD compared with normal tissues, which was verified through qRT-PCR in different cell lines (P < 0.05), and associated with patients’ clinical stage, tumor size, and lymphatic metastasis status (all P < 0.01)." (PMID 33842535, 2021). "Moreover, using multidimensional analysis, we assessed the coexpression and functional network associated with GNPNAT1 in LUAD and learned its role in tumor immunity." (PMID 33178836, 2020). "GNPNAT1 was validated upregulated in tumor tissues in TCGA-LUAD and GEO cohorts." (PMID 33178836, 2020). "In TCGA-LUAD cohort, we compared the expression of GNPNAT1 in tumor and adjacent tissues, and the unpaired (p value = 3.28e−29) and paired (p value = 4.425e−19) tests both indicated that the expression of GNPNAT1 in the tumor was elevated." (PMID 33178836, 2020). "Hence, we speculate that the targeting GNPNAT1 become an effective combined method to sensitize immunotherapy, and it even become a brand-new and universal anti-tumor therapy target in TNBC." (PMID 37215111, 2023). "However, further research is needed to explore the role of GNPNAT1 as a tumor metabolism gene, whether it is an influencing factor in LUAD progression, and the related mechanisms." (PMID 33686019, 2021). "Hence, we speculated that the overexpression of GNPNAT1 might affect the function of tumor-infiltrating immune cells by regulating glycosylation modifications." (PMID 33842535, 2021). "GNPNAT1 is abnormally expressed in LUAD tissues, which can increase tumor cell stemness and promote the division and invasion of cancer cells." (PMID 39959839, 2025). "The Wilcoxon test further demonstrated a positive correlation between GNPNAT1 expression and clinicopathological characteristics, including TNM stage, tumor stage, and lymph node metastasis stage." (PMID 39062049, 2024). "The results of the ESTIMATE analyses suggested that the high GNPNAT1 expression group had lower immune score and ESTIMATE score than the low GNPNAT1 expression group, while the tumor purity score was higher." (PMID 37215111, 2023). "Two DRGs, GNPNAT1 and MORF4L2, exhibited strong correlations with survival prognosis and tumor-infiltrating immune cells (CD8+ T cells, macrophages, etc.)in the analysis above." (PMID 37033959, 2023). "Similarly, we explored that increasing expression of GNPNAT1 has a positive correlation with M2 macrophages, while has a negative correlation with total macrophages, which possibly alters the composition of macrophages in the tumor environment and thereby affected the progression of BRCA patients." (PMID 37215111, 2023). "Subsequently, we applied RT-PCR to detect the expression level of GAPDH, GNPNAT1, HTATIP2, MFI2, PKP2, RGS20, and CHRDL1 in these 10 tumor tissues." (PMID 35186082, 2022). "The analysis revealed that GNPNAT1 had a converse correlation with the infiltration of B cells, CD4+ T cells, and dendritic cells, which all had an anti-tumor effect in NSCLC." (PMID 33842535, 2021).
tumor (continued). "At the cell level, the CCLE database revealed that GNPNAT1 was up-regulated in NSCLC and other 39 different tumor cells." (PMID 33842535, 2021). "The expression level of CCL20, F2, GNPNAT1 and NT5E in the tumor samples was significantly higher than that in normal tissues, while the expression level of B3GALT2, and VSIG2 displayed an opposite expression pattern." (PMID 34787244, 2021). "In PDAC, we revealed a slight increase of GNPNAT1 and UAP1 expression and a significant overexpression of GFAT1 in tumor tissues compared with normal counterparts." (PMID 32149084, 2020). "Similarly, another independent GSE3167 dataset also displayed the increased mRNA expression levels of GFPT1, PGM3, and UAP1 and the decreased GFPT2 level in tumor tissues, while the data of GNPNAT1 gene were not available in this dataset." (PMID 36158580, 2022).
cancer (11 papers, 2019 to 2025). A tumor composed of atypical neoplastic, often pleomorphic cells that invade other tissues. "We also observed associations between GNPNAT1 expression and immune cell infiltration levels across different cancer types." (PMID 33686019, 2021). "We also observed associations between GNPNAT1 expression and immunomodulators across different cancer types." (PMID 33686019, 2021). "Mechanistically, GNPNAT1 promoted cancer cell metastasis via repressing ubiquitination degradation of Snai2 in LUAD." (PMID 39062049, 2024). "In contrast, reduced expression of GNPNAT1 in castration-resistant prostate cancer cells significantly increased cancer cell proliferation and tumorigenic capacity." (PMID 37838167, 2023). "In this study, we demonstrated that GNPNAT1 was significantly overexpressed in nine out of the 23 human cancer tissues." (PMID 37215111, 2023). "We analyzed GNPNAT1 genetic alterations and co-occurrence networks, and the functional networks of these genes showed that GNPNAT1 participates in multiple steps of cell cycle transition and in the development of some cancers." (PMID 33686019, 2021). "We assessed the correlation between GNPNAT1 expression and cancer immune infiltrates and showed that GNPNAT1 expression is correlated with several immune cells, chemokines, and immunomodulators in LUAD." (PMID 33686019, 2021). "Functional network analysis suggested that GNPNAT1 regulates cell cycle, ribosome, proteasome, RNA transport, and spliceosome signaling through pathways involving multiple cancer-related kinases and E2F family." (PMID 33178836, 2020). "Correlations between GNPNAT1 and cancer immune characteristics were analyzed via the Estimation of Stromal and Immune cells in Malignant Tumor tissues using Expression data (ESTIMATE) and Cell-type Identification by Estimating Relative Subsets of RNA Transcript (CIBERSORT) R package." (PMID 39062049, 2024). "Mechanistically, we found that GNPNAT1 could promote cancer cell metastasis by stabilizing Snai2 in LUAD." (PMID 39062049, 2024). "Moreover, we described the correlation of GNPNAT1 expression with chemokines or receptors across different cancer types." (PMID 33686019, 2021). "The relationship between glucosamine 6-phosphate N-acetyltransferase 1 (GNPNAT1/GNA1) and cancer was seldom reported." (PMID 35186082, 2022). "In some datasets where GFAT expression was not significantly increased, one of GNPNAT1, PGM3, or UAP1 was highly expressed in cancer tissues." (PMID 31645543, 2019).
metabolism disorders (1 paper, 2022). "PPARA, PPARGC1A, and PPARGC1B, which are involved in the fatty acid oxidation of PLN-KO hiPSC-CMs, began to decline at day 30, while genes involved in glucose utilization, such as GNPNAT1, PGM3, and GFPT1, were upregulated, indicating that energy metabolism disorders began to occur." (PMID 35334215, 2022).
GNPNAT1 also shares sentences with these, for which no sentence is quoted: infection (2 papers); aspergillosis (1); benign prostatic hyperplasia (1); cutaneous melanoma (1); hepatocellular carcinoma (1); Hypertension (1); malaria (1); non-small cell lung carcinoma (1); oral squamous cell carcinoma (1); osteosarcoma (1); toxoplasmosis (1); uveal melanoma (1).